BRCA1 (BRCA1 DNA repair associated)
Diseases named in the same sentence as BRCA1 in open-access papers (continued):
Sharing a sentence is not in itself a finding about the gene and the disease.
breast cancer (continued). "The association patterns between these common variants and breast cancer risk for BRCA1 and BRCA2 mutation carriers are in general different, and mostly reflect differences in the associations of these single-nucleotide polymorphism (SNPs) with estrogen receptor (ER) status of breast cancer." (PMID 22348646, 2012). "In addition, a genetic linkage cohort study consisting of 214 breast cancer and breast-ovary cancer families combined, revealed that 90% of the patients harbored mutations in their BRCA1 gene." (PMID 22685544, 2012). "Given the importance of tumour morphology features to inform treatment choices and to identify BRCA1 mutation carriers or BRCA1 promoter methylation, we are now interested in identifying tumour morphology features that predict familial risk of early-onset breast cancer." (PMID 22929433, 2012). "We recently showed that two breast tumour morphology features, trabecular growth pattern and high mitotic index, were sufficient to identify almost all BRCA1 mutation carriers in our population-based sample of breast cancer cases diagnosed before the age of 40 years." (PMID 22929433, 2012). "In order to study BRCA1/2 mutation spectra in the Lebanese population, 72 unrelated patients with a reported family history of breast and/or ovarian cancers or with an early onset breast cancer were tested." (PMID 22713736, 2012). "While it has been reported that the risk of contralateral breast cancer in patients from BRCA1 or BRCA2 positive families is elevated, little is known about contralateral breast cancer risk in patients from high risk families that tested negative for BRCA1/2 mutations." (PMID 23216834, 2012). "Many studies have examined the relationship between breast cancer and BRCA1 mutation." (PMID 22735547, 2012). "Potential use of RAD21 as a predictive and prognostic marker in familial breast cancers is hence feasible and may therefore take into account the patient's BRCA1/2 mutation status." (PMID 22537934, 2012). "We also evaluated whether rs2180341 was associated with breast cancer risk in BRCA1 or BRCA2 mutation carriers, by genotyping 5,381 mutation carriers from 11 studies in the Consortium of Investigators on Modifiers of BRCA1/2 (CIMBA)." (PMID 22768030, 2012). "Discovery of the breast cancer-predisposition genes BRCA1 and BRCA2 has enabled us to identify carriers accurately, to target the reduction of risk of breast and ovarian cancers in carriers, and to develop a new generation of targeted therapies (PARP inhibitors)." (PMID 23116406, 2012). "Studies of high-risk families quantifying the extent of risk variation have suggested that other genetic factors may modify the risk of breast cancer associated with BRCA1 mutations." (PMID 22347400, 2012). "Relatives of families with BRCA1 mutations were significantly younger at first breast cancers than those from families with BRCA2 mutations (P < 0.001) and both were significantly younger than patients from BRCA1/2 negative families (P < 0.001 and P < 0.001, respectively)." (PMID 23216834, 2012). "Likewise, the lifetime risk of developing breast cancer is been reported as high as 80% and 50% for BRCA1 and BRCA2 mutation carriers, respectively; although it varies between different populations and ethnicities." (PMID 22655046, 2012). "BRCA1, one of the most well studied breast cancer genes, contains numerous genetic variants." (PMID 22811759, 2012).
breast cancer (continued). "Moreover, mutation of the NES abolished the ability of full-length BRCA1 to regulate centrosome amplification in DNA damaged BRCA1-mutant breast cancer cells." (PMID 24278741, 2012). "The fact that BRCA1/p220-associated and TN/BL breast cancers commonly show early onset and aggressive diseases expressing no-/low-BRCA1/p220, made us wonder whether BRCA1/p220 loss enhances the TN/BL phenotype via upregulating BRCA1-IRIS." (PMID 22431556, 2012). "Finally, PIF1 variant P109L, which was found in a BRCA1 mutation carrier with particularly early onset breast cancer as well as in 1 of 198 controls, is predicted to be deleterious." (PMID 22347400, 2012). "Up to 50% of women diagnosed with breast cancer, younger than 50 years, and women who have a family cancer history may have mutations in BRCA1 or BRCA2." (PMID 23116406, 2012). "Baseline characteristics of breast cancer cases and controls with BRCA1 and BRCA2 mutations." (PMID 22405187, 2012). "Women with BRCA1/p220 mutations are predisposed to early-onset breast cancer." (PMID 22431556, 2012). "Germline BRCA1 or BRCA2 mutations account for 20–30% of familial clustering of breast cancer." (PMID 23284877, 2012). "For example, BRCA1 mutations occur in approximately 20 % of familial breast cancer cases." (PMID 22706632, 2012). "PDAC is seen in some breast cancer families with BRCA1 and BRCA2 mutations." (PMID 22873581, 2012). "Interestingly, nuclear Kaiso was also abundant in BRCA1-associated breast cancer (p<0.001) and invasive breast cancer overexpressing EGFR (p = 0.019)." (PMID 22662240, 2012). "Defects in breast cancer susceptibility proteins BRCA1 and BRCA2 (FANCD1) result in HR defects." (PMID 22693661, 2012). "Life time risks of breast cancer among BRCA1/2 mutation carriers are 82%." (PMID 22606018, 2012). "Furthermore, common variants of the BRCA1 wild-type allele have also been recently suggested to modify the risk of breast cancer in BRCA1 mutations carriers." (PMID 22513257, 2012). "A woman who carries a mutation in BRCA-1 has a risk of 60–80% for developing breast cancer." (PMID 22675372, 2012). "A stronger association of SNP rs2046210 with ER− tumours is also consistent with the report from the Consortium of Modifiers of BRCA1/2 (CIMBA) that the same allele is associated with an increased Hazard Ratio of breast cancer in BRCA1 mutation carriers (who predominantly develop ER− tumours)." (PMID 22879957, 2012). "Loss of BRCA1 function in basal breast cancer is in agreement with this finding." (PMID 22082486, 2012). "However, results from a recent population-based study are in line with our risk estimates for contralateral breast cancer in BRCA1 and BRCA2 carriers." (PMID 23216834, 2012). "The risk reduction potential for bilateral oophorectomy may be higher in a BRCA1 &2 carrier who is known to be at a higher risk of both ovarian and breast cancers." (PMID 23308325, 2012). "Over 1700 unique BRCA1 mutations have been reported to the Breast Cancer Information Core Database." (PMID 22737296, 2012). "In a population-based multiethnic series of female breast cancer patients, BRCA1 mutation was prevalent in 3.5% of Hispanics but only 2.2% of non-Hispanic whites, suggesting differential contribution of BRCA1 mutations to familial breast cancers in Hispanic women." (PMID 22238615, 2012).
breast cancer (continued). "For BRCA1 mutation carriers, only SNP rs10771399 at 12p11 was associated with the overall risk of breast cancer, whereas SNPs rs10995190 at 10q21, rs1011970 at 9p21, rs865686 at 9q31.2 and rs1292011 at 12q24 were associated with breast cancer risk for BRCA2 mutation carriers." (PMID 22348646, 2012). "Triple-negative (TN) tumours are the predominant breast cancer subtype in BRCA1 mutation carriers." (PMID 22333603, 2012). "Therefore, we conclude that contralateral breast cancer risk for familial non-BRCA1/2 breast cancer is essentially in the same range as for women with sporadic breast cancer." (PMID 23216834, 2012). "Risk of breast cancer up to 80% is usually observed in BRCA1 and BRCA2 mutation carriers." (PMID 22503188, 2012). "The other 2 (BRCA1) mutations were found in patients with early onset breast cancer." (PMID 23519070, 2012). "For early-onset breast cancer, we showed that only two key features could better predict BRCA1 mutation carriers than family history and/or ER and PR tumour status." (PMID 22929433, 2012). "The wide variation in reported prevalence of BRCA1/2 mutation in patients with early onset could be related to variation in number with family history of breast cancer in these studies." (PMID 22382806, 2012). "BRCA1/2 mutations, thus, account for 5–10 percent of all breast cancers." (PMID 22984553, 2012). "Whether cancers from these organs are genetically related to breast cancer or BRCA1/2 mutation requires confirmation." (PMID 22382806, 2012). "With the discovery of the BRCA1 gene and other genetic mutations associated with breast cancer, it has been established that hereditary mutations account for up to 5% of patients presenting with breast cancer." (PMID 23519070, 2012). "BRCA1 is rarely mutated in sporadic mammary tumors overall, but more frequently in TN tumors." (PMID 22082486, 2012). "The genomic region of SLX4, comprising all exons and exon-intron boundaries, was sequenced in 94 Spanish familial breast cancer cases that match a criterion indicating the potential presence of a highly-penetrant germline mutation, following exclusion of BRCA1 or BRCA2 mutations." (PMID 22401137, 2012). "Among women with a BRCA1 mutation and breast cancer, choice of chemotherapy is a critical issue." (PMID 22817698, 2012). "However, homozygous mice with certain hypomorphic Brca1 alleles can survive to adulthood and display an increased susceptibility to a range of tumors, including mammary carcinomas." (PMID 22347400, 2012). "Several studies have shown that risk-reducing bilateral mastectomy reduces the risk of breast cancer among BRCA1 mutation carriers by approximately 90% and additional risk-reducing bilateral salpingo-oophorectomy improves this parameter by only 5% to a total of 95%." (PMID 22032251, 2011). "The BRCA1-like aCGH pattern may also be present in sporadic breast cancers, which frequently show evidence of impaired BRCA1 function due to other causes than mutation, for example, methylation." (PMID 22032731, 2011). "This information could be clinically useful in helping decide where limited resources for counselling and mutation testing for BRCA1 carriers in women with early-onset breast cancer might best be directed." (PMID 21343941, 2011). "We can speculate that mutations in BRCA1/2 or other genes induce faster telomere attrition during life time increasing the probability of genomic instability and the risk of developing breast cancer." (PMID 21829373, 2011). "Because of this high risk of breast cancer, women with a mutation in either the BRCA1 or BRCA2 gene are offered breast cancer surveillance, which includes annual clinical breast examination, annual mammography and annual contrast enhanced magnetic resonance imaging (MRI) of the breast." (PMID 21864353, 2011).
breast cancer (continued). "It is currently unknown how these alleles are associated with different breast cancer subtypes in BRCA1 and BRCA2 mutation carriers defined by estrogen (ER) or progesterone receptor (PR) status of the tumour." (PMID 22053997, 2011). "However, screening in this age group in the Netherlands is only recommended when women are at high risk for breast cancer, for instance because of an inherited BRCA1 or BRCA2 gene mutation." (PMID 21364575, 2011). "The common pathological features of breast tumors arising in breast cancer 1, early onset (BRCA1) gene mutation carriers, including the basal-like phenotype and ER negativity, led to the proposition that BRCA1 function regulates stem/progenitor cell proliferation and differentiation." (PMID 22110403, 2011). "All of the other studies we reviewed did reveal a difference in CBC ranging from 1% to 11% in controls to 25% to 42% in mutation carriers when BRCA1/2 mutation carriers were compared to patients with familial, non-BRCA1/2-associated breast cancer and/or sporadic controls." (PMID 22295226, 2011). "A clear indication that BRCA1 may be associated with sensitivity to cisplatin came from studies of breast cancer in mice." (PMID 24212667, 2011). "In addition, breast cancers arising in BRCA1 and BRCA2 mutation carriers are heterogenic for LOH, suggesting haploinsufficient effects in pathogenesis." (PMID 21958427, 2011). "Previous studies have indicated that the majority of newly diagnosed breast cancer patients at high risk of being BRCA1/2 mutation carriers will accept the invitation to undergo RGCT, and that the DNA test results can have a substantial impact on the choice of surgery." (PMID 21219598, 2011). "The minor allele of FGFR2 SNP rs2981582 was associated with a significantly higher risk for PR-positive breast cancer for BRCA1 mutation carriers (per-allele HR for PR-positive = 1.29, 95% CI: 1.10 to 1.51, HR for PR-negative = 0.93, 95% CI: 0.87 to 1.00, P-heterogeneity = 7 × 10-4)." (PMID 22053997, 2011). "Since the MLPA assay can identify BRCA1-deficient breast cancer patients, this method could be applied both for clinical genetic testing and as a predictor of treatment benefit." (PMID 22032731, 2011). "This could indicate that loss of BRCA1 with c-Myc overexpression might lead to the development of basal-like breast cancer." (PMID 21668996, 2011). "Some of these changes have been characterized to provide a clear contribution to the development and/or progression of the cancer and include overexpression of HER2/neu in about 20% of breast cancer, and hereditary mutations in BRCA1 or BRCA2 in approximately 5% of breast cancers." (PMID 21541295, 2011). "The risk of contralateral breast cancer was estimated for patient subgroups defined by age group, gene (BRCA1 vs BRCA2), number of affected first-degree relatives, and by treatment received (surgery, chemotherapy, tamoxifen, radiotherapy, and ovarian ablation)." (PMID 21487411, 2011). "BRCA1-deficient mouse mammary tumor cells are selectively sensitive to an inhibitor of EZH2." (PMID 24212667, 2011). "About 5–10% of young women diagnosed with breast cancer carry germline mutations in BRCA1." (PMID 21343941, 2011). "In breast cancer patients, c-Myc amplification was found more often in patients with BRCA1 deficiency than in patients with normal BRCA1, suggesting that c-Myc amplification could be linked to decreased BRCA1 but the mechanism is poorly understood." (PMID 21668996, 2011). "Topotecan inhibited growth of mammary tumors in genetically engineered BRCA1-deficient mice." (PMID 21819606, 2011). "However, there remains a need to identify additional susceptibility genes as it has become increasingly evident that BRCA1/BRCA2 mutations cannot explain all cases of familial breast cancer." (PMID 21835029, 2011). "Only two reports from Brazilian breast-cancer affected patients have suggested that a founder BRCA1 mutation, c.5266dup, may be encountered at a significant prevalence." (PMID 22185575, 2011).
breast cancer (continued). "However, these mice were BRCA1-proficient and at risk for breast cancer because of overexpression of transgenic erbB2 (Her2), which is a member of the EGFR family and a direct target for the drugs used in those studies, that is, lapatinib or gefitinib." (PMID 21396117, 2011). "Our group has employed aCGH to assess the genomic patterns of BRCA1-mutated breast cancers." (PMID 22032731, 2011). "Conversely, loss of BRCA1 function might impair structural cues of terminal differentiation and, consequently, increase risk of breast cancer characterized by the basal-like tumor type." (PMID 22110403, 2011). "Here, we sought to identify putative gene fusion mRNA transcripts in BRCA1-mutated breast cancers." (PMID 22032724, 2011). "Allele "A" of SNP rs13387042 at 2q35 was associated with a significantly higher risk of PR-positive breast cancer for BRCA1 mutation carriers (HR for PR-positive breast cancer = 1.16, 95% CI: 1.01 to 1.33; HR for PR-negative = 0.97, 95% CI: 0.91 to 1.04, P-heterogeneity = 0.034)." (PMID 22053997, 2011). "Additionally, as in human BRCA1-associated breast cancer, increased expression of several components of the IGF axis is seen in liver, normal mammary tissue and mammary tumors of these mice along with increased levels of IGF-1 in serum." (PMID 21888628, 2011). "In their study of relatives of BRCA1 mutation carriers, they reported a 25-year contralateral breast cancer risk of 63% for women younger than 40 years of age at time of first breast cancer (annual risk 2.5%) compared with 20% for those older than age 50 years (annual risk 0.8%)." (PMID 21487411, 2011). "Although previous studies have identified a group of high penetrance susceptibility genes and loci of breast cancer, such as BRCA1, BRCA2, and CHEK2, these genes could only explain a small part of the genetic risk of breast cancer." (PMID 21912531, 2011). "BRCA1 c.4034delA was initially described as a low penetrance breast cancer mutation." (PMID 22032251, 2011). "Based on their involvement in DDR and importance in BRCA1-mediated DNA damage recognition it was considered possible that mutations in these genes might contribute to hereditary predisposition to breast cancer." (PMID 21774837, 2011). "The lifetime risk of breast cancer in BRCA1- and BRCA2-mutation carriers is 45–80%." (PMID 22312502, 2011). "Among BRCA1 carriers, each first-degree relative affected with breast cancer before 50 years of age was associated with a 40% increase in the risk of contralateral breast cancer." (PMID 21487411, 2011). "In addition, we show how this kit can be used to identify both BRCA1-mutated breast cancers and sporadic cases with a BRCA1-likeaCGH profile and we present evidence that the kit can be used for treatment selection." (PMID 22032731, 2011). "The breast cancer susceptibility gene BRCA1 is located on chromosome 17q12-21." (PMID 22016618, 2011).